TNF (tumor necrosis factor)
Diseases named in the same sentence as TNF in open-access papers (continued):
Sharing a sentence is not in itself a finding about the gene and the disease.
Stroke (continued). "The expression of pro-inflammatory factors such as tumor necrosis factor (TNF), interleukin-1 (IL-1) and interleukin-6 (IL-6) is increased in the infarct region, and both infiltrating and resident cells jointly regulate the inflammatory response after stroke." (PMID 38203348, 2023). "Yang and coworkers also reinforced the role of IL-6 and other cytokines like IL-1β and TNFα in disruption of blood–brain barrier (BBB), leading to neurological degeneration in such diseases as Alzheimer’s disease (AD), stroke, multiple sclerosis (MS), and posttraumatic brain injury (TBI)." (PMID 38093175, 2023). "This literature review focused on only TNF alpha since it is involved in the occurrence, development, and prognosis of stroke, although some studies do not support TNF alpha as a clear marker of stroke." (PMID 37065345, 2023). "Notably, TNF-α is a well-characterized proinflammatory cytokine, and increased TNF-α expression is observed in the early phase of stroke in rodent models and postmortem human brain tissues." (PMID 37486903, 2023). "Among them, tumor necrosis factor-α (TNF-α), interferon-γ (IFN-γ), and IL-6 are increased after stroke, and this process may be explained by “cytokine storm”." (PMID 36777635, 2023). "Although this study confirmed up-regulation of NR4A1 in microglia after stroke in postmortem human brains, it is unclear whether NR4A1 modulates TNF expression via the same posttranscriptional mechanism in human microglia." (PMID 37490433, 2023). "To date, no clinical trials have assessed the potential benefit for stroke prevention of TNF-α antagonists in patients with CV diseases." (PMID 37762627, 2023). "Plasma endostatin, PDGF-BB, TNF-α and VEGF levels were higher in stroke patients vs HVs." (PMID 37129729, 2023). "I/R caused an increase in pro-inflammatory cytokines (IL-1beta, IL-6, TNF-alpha) at 6-h or 24-h of I/R, but not in the subacute (72-h) phases of stroke." (PMID 37822799, 2023). "In this study, we report for the first time that stroke in T2DM mice induces earlier and higher inflammatory factor, cytokine, and acute phase response protein expression such as SAA, NLRP3, IL-1β, IL-6, TNFα, and TLR4 in the liver compared to heart and kidney." (PMID 36968490, 2023). "The work by Liu and colleagues is novel and intriguing as it identifies a previously unidentified role of NR4A1 as an RNA-binding protein, highlights a new regulatory mechanism of TNF expression in microglia, and underscores a key function of NR4A1 in microglial polarization and stroke outcomes." (PMID 37490433, 2023). "After either experimental or human stroke, cerebral expression of TNF and of its receptors, TNFR1 and TNFR2, increases, whereby microglia and infiltrating macrophages represent the major source of TNF-α in the acute phase after ischemia." (PMID 36674674, 2023). "Although several studies reported the elevation of TNF-α and nitric oxide in stroke, these factors were not independent predictors of outcome or severity." (PMID 37446092, 2023). "Similarly, herein, we revealed that the IL‐1β, TNF‐α, IL‐6 and IFN‐γ mRNA contents enhanced after the development of ischemia in tMCAO stroke rats, whereas, these expressions were diminished after engeletin treatment." (PMID 37132060, 2023). "Notably, blocking TNF-α and IFN-γ significantly ameliorated stroke phenotypes in Vdr conditional knockout mice." (PMID 36890539, 2023). "Our data also showed higher levels of IFN-β, IFN-γ, and TNF-α after stroke, regardless of factors such as age, sex, time of treatment, and stroke volume." (PMID 37587512, 2023). "Beyond IL‐10, the development of poststroke infections also correlates with lower TNF‐α levels and the consequent decrease in the TNF‐α/IL‐10 ratios at day 2 after stroke, this latest supporting a role of the Th1/Th2 shift in patients suffering from such complications." (PMID 35971650, 2022).
Stroke (continued). "Although they are not stroke-specific markers, such as interleukin 1 (Il-1), interleukin 6 (Il-6) or tumour necrosis factor-α (TNF-α), they suggest the existence of immunological activation in the course of the inflammatory process and tissue damage." (PMID 35330458, 2022). "For treatment in preclinical models of stroke or PD in the mouse, an 8D3-derived TfRMAb–TNFR fusion protein was engineered and expressed, and this fusion protein retained high affinity binding to both the mouse TfR1 and TNFα." (PMID 35745855, 2022). "Many inflammatory factors and chemokines were upregulated in IL-1α-, TNFα- and C1q-treated astrocytes, indicating that A1 astrocytes may induce inflammatory and immune responses to disrupt BBB integrity after stroke." (PMID 35656116, 2022). "According to a previous systematic review, a single high dose of vitamin D3 significantly reduced levels of inflammatory cytokines (interleukin-6 and tumor necrosis factor-alpha, TNF-α), improved endothelial function in patients with a history of stroke, type 2 diabetes, and cardiovascular function." (PMID 36176639, 2022). "Overexpression of miR-126-3p and -5p also downregulated the expression of pro-inflammatory cytokines interleukin (IL)-1β and tumor necrosis factor (TNF)-α, accompanied by reduced protein level of cell adhesion molecules VCAM-1 and E-selectin three days after stroke." (PMID 35346266, 2022). "The pro-inflammatory (TNF-α, IL-1β, IL-6, IL-12 p40, and MIP-1α), and the anti-inflammatory (IL-4 and IL-10) mediators were examined by ELISA in IRF5 or IRF4 CKO aged mice plasma, 3 days after stroke." (PMID 35963621, 2022). "To evaluate the effects of serpinA3N on pro‐inflammatory responses after stroke, we measured the expression of inflammatory cytokines interleukin (IL)‐6 and tumor necrosis factor (TNF)‐α and found that IL‐6 and TNF‐α were significantly lower in serpinA3N‐overexpressed mice at 24 h poststroke." (PMID 34897996, 2022). "Stroke-induced cytokines (IL-6, TNF-α, and IL-1β) and MCP-1 and CCR2 mRNA levels were significantly higher in the diabetic brain compared to control at 1 day after MCAO, and this increased expression was sustained until 3 days post-stroke." (PMID 35784349, 2022). "TNF-α is an important mediator of the inflammatory response, which can activate microglia and astrocytes, leading to leakage of the BBB and aggravating the progression of stroke." (PMID 35559267, 2022). "Even though there was a trend of reduced TNF-α and Fractalkine release from monocytes of stroke patients, this trend was not statistically significant." (PMID 36277912, 2022). "In an experimental stroke model, the cytokines IFN-γ, IL-6, and CXCL1 are elevated in the serum within a matter of hours, and circulating and splenic immune cells increase the production of IL-6, IL-2, TNF-α, IFN-γ, and CCL2." (PMID 36446955, 2022). "Interestingly, we found a positive correlation between the concentration of IL-6 and TNF-α in patients with AIS assessed in <4.5 h and 1 day after the stroke, which means that the concentration of IL-6 rises with the increase in TNF-α concentration." (PMID 36142524, 2022). "On the other hand, MEDS-23 did not significantly reduce post-stroke mortality nor did it prominently influence the levels of brain IL-6 and TNF-α in post-stroke rats." (PMID 35053779, 2021). "These cultured A2 astrocytes could be induced to the A1 phenotype by TNF-α and IFN-γ in the OGD condition; IFN-γ may be the most potent A1 inducer in the stroke environment." (PMID 34445510, 2021). "The plasma level of IL-6, but not TNFα, sIL-6R, and IL-1ra, was higher in patients who developed depressive symptoms at 3 months after stroke (median: 4.7 vs 3.4 pg/mL, P = 0.06)." (PMID 33903586, 2021). "In addition to the major reduction in stroke occurrence, a statistically significant decrease in inflammatory burden (ESR, CRP) followed anti-TNF treatment initiation." (PMID 35095905, 2021).
Stroke (continued). "Three of our patients received anti-TNF therapy; only one of them had a significantly elevated level of TNF-α before, and all showed a good response, with no stroke occurring after initiation." (PMID 33757531, 2021). "Studies have shown that neural stem cells undergo apoptosis by TNF-α in vitro, suggesting that TNF-α has a negative effect on post-stroke neurogenesis." (PMID 34831273, 2021). "This was corroborated by literature publishing that TNF-α, IL-1B, IL-6 and IL-18 also independently predicted the occurrence of PSD in the acute to subacute period, and elevated IL-6, IL-10 and TNF-α correlates with PSD at one to three months post stroke." (PMID 33919670, 2021). "The inflammatory cytokines, tumor necrosis factor-alpha (TNF-α) and interleukin-6 (IL-6), are generally considered to be representative contributors to neuroinflammation in ischemic stroke and are therefore promising potential targets in future stroke therapy." (PMID 33953667, 2021). "Non-stimulated saliva of stroke patients was characterized by significantly higher concentration (↑135%), output (↑196%), and specific amount (↑170%) of TNF-α." (PMID 34433866, 2021). "Interestingly, the level of TNF-α in NWS correlates more strongly with the cognitive and physical functional status of stroke patients." (PMID 34433866, 2021). "Moreover, we determined the effects of MEDS-23 on levels of the inflammatory mediators IL-6, TNF-α and PGE2 in various brain regions of post-stroke rats." (PMID 35053779, 2021). "On the contrary, TNF-α production in response to PMA predicted poor functional outcomes even after accounting for the main prognostic factor, which is the baseline severity of the stroke." (PMID 32719588, 2020). "In the Western blot assessment, the protein levels of TNF-α and IL-1β were increased, whereas no change was detected in IL-6 and IL-10 protein levels in the stroke mice at 3 days after stroke." (PMID 32010477, 2020). "Therefore, formulations of TNF inhibitors with better BBB penetrance and selective inhibition of solTNF have been designed and tested in preclinical stroke models." (PMID 32503645, 2020). "These cytokine-related genes, such as TNF-α, iNOS, and TNF-β, which are pro- or anti-inflammatory, may contribute to the impairment of neuronal and brain damage after stroke." (PMID 33177990, 2020). "The exogenous recombinant Prx1 could block the inhibitory effects of PJ34 on post-stroke inflammation in the male MCAO mice,as the reduction of Iba-1, iNOS, and TNF-α mRNA levels induced by PARP-1 inhibition were reversed by Prx1." (PMID 32317937, 2020). "TNF-α and IL-6 are the main inflammatory factors involved in brain tissue damage; they are expressed at high levels in the early stage of ACI and are related to the infarct volume, neurological deficit, and prognosis after stroke." (PMID 33299456, 2020). "mRNA expression of pro-inflammatory cytokines, including IL-6, TNF-α, and CXCL1, were quickly increased after stroke and peaked at 24 h, whereas IL-1β, COX-2, and MCP-1 levels peaked at 48 h after stroke." (PMID 32867781, 2020). "Atenolol, at higher doses (more than 400 nM), increased the secretions of TNF-α from stroke-Mo (p < 0.05) but did not have any effect on TNF-α release from Mo harvested from healthy controls after 24 hours of exposure." (PMID 32802081, 2020). "A recent report has issued that CD200R1 is expressed on infiltrating lymphocytes, not on MG, and CD200R1 KO stroke brains showed higher concentrations of TNF‐α and IL‐1β in ischemic brain tissue of KO mice compared with WT controls at day 7 after stroke." (PMID 33067924, 2020). "Pro-inflammatory cytokines, such as tumor necrosis factor alpha (TNF-α), interleukin 6 (IL-6), interleukin 1 beta (IL-1β), and monocyte chemoattractant protein-1 (MCP-1), were significantly increased in the CLEC14A-KO mice after stroke." (PMID 32019570, 2020).
Stroke (continued). "On the contrary, for all other cytokines measured (IL-1β, MCP-1, TNF-α, IL-1RA, and IL-6), secretions were reduced only from cocultures with healthy monocytes, and not from stroke-Mo at 24 hours." (PMID 32802081, 2020). "Among the enriched pathways of S-module 1, the most frequently enriched category signal transduction, including calcium signaling pathway, TNF signaling pathway, sphingolipid signaling pathway, cGMP-PKG signaling pathway, and HIF-1 signaling pathway, exhibited a close relationship with stroke." (PMID 31772561, 2019). "In the pathological progression of stroke, gelatinases including MMP-2 and MMP-9, possess the ability to activate numerous pro-inflammatory agents, including chemokine CXCL-8, interleukin 1β, and tumor necrosis factor α." (PMID 30953513, 2019). "In the present study, L-4F treatment significantly decreases TNFα and PAI-1 expression in the ischemic brain which may partially contribute to L-4F treatment-induced vascular and WM protection in T2DM stroke mice." (PMID 31708728, 2019). "It has been shown that intravenous administration of etanercept is not therapeutic during stroke rehabilitation because biologic TNF inhibitors can be reengineered for BBB penetration." (PMID 31031649, 2019). "In order to explore the roles of astrocytes in post-stroke inflammation, the levels of inflammatory factors were detected in primary astrocytes at 0 h, 6 h, 12 h, 24 h, and 48 h after 6-h OGD, including TNF-α, IL-6, IL-10, inducible nitric oxide synthase (iNOS), IL-1β, and CXCL10." (PMID 31426811, 2019). "We can infer that it is formatting an inter-module coupling connectivity between H-modules and stroke pathological modules, which contributed to pharmacological mechanism of HLJDD in stroke, mainly involving the TNF signaling pathway, the HIF signaling pathway, and the PI3K-Akt signaling pathway." (PMID 31772561, 2019). "Through the acquisition of a classically activated state as a result of astrocytic signals and/or microglial CD8 signalling, they secrete pro-inflammatory cytokines including TNF-α, IL-1α that induce neurotoxic astrocytes and disrupt the integrity of the BBB post-stroke." (PMID 31312180, 2019). "Analysis of fluorescence intensities showed a decrease in expression of inflammatory markers CD45 and TNF-alpha in the spleens of the 30m and 60m exercise groups of stroke rats compared with non-exercise stroke rats." (PMID 30941660, 2019). "For the treatment of DAD2, a study showed that all patients undergoing anti-tumor necrosis factor-alpha (anti-TNFα) therapy did not develop stroke after treatment initiation." (PMID 31938632, 2019). "We examined BDNF reactivity in TNF-α+ and IL-β+ cells (not restricted to macrophages) two days after stroke." (PMID 30405724, 2018). "With regard to therapeutic intervention, G-CSF, IL-1β, IP-10, MCP-1, MIP-1α, MIP-1β, RANTES, TNF-α, MMP-2, and MMP-8 were substantially reduced in OPN-/- mice seven weeks following stroke, and these mice exhibited less secondary neurodegeneration in the peri-infarct location." (PMID 30417081, 2018). "IL‐6, but not TNF‐α, measured at baseline has been considered to be an independent predictor of worsening in the first 24 hr after stroke (Muir, Weir, Alwan, Squire, & Lees, 1999)." (PMID 29484258, 2018). "RIC alone without subsequent stroke obviously promoted plasma IL-6 expression without any impact on the concentration of IL-10 and TNF-α." (PMID 30115811, 2018). "Interestingly, microglial intracellular pro‐inflammatory cytokine TNF‐α significantly correlated with NDS at 3 and 10 days after stroke." (PMID 29131464, 2018). "Ischemic damage and MSC transplantation after stroke did not induce the Iba-1+ cells to produce TNF-α or IL-1β either." (PMID 30405724, 2018). "It is noteworthy that this study is the first to show that (–)- or (+)-naloxone inhibits basal TNF-α secretion from stroke-activated microglia/macrophages without extra stimulus." (PMID 29766045, 2018).
Stroke (continued). "Additionally, we found that the concentrations of TNF-α, IL-6, IFN-r and IL-10 were significantly increased post-stroke." (PMID 30013463, 2018). "Moreover, plasma TNF-α and IGF-1 levels increased and decreased, respectively, in stroke patients, and miR-424 levels in lymphocytes and neutrophils were both inversely correlated with plasma TNF-α, IL-10, or IGF-1 levels." (PMID 29675290, 2018). "In contrast, exposure to BALF from Stroke or Sham animals did not change the phagocytic capability of alveolar macrophages, or the gene expression of IL-6 and TNF-α." (PMID 30290827, 2018). "Exposure to BALF from Stroke or Sham animals did not change alveolar macrophage behavior, or gene expression of TNF-α and IL-6." (PMID 30290827, 2018). "Moreover, we found that pro-inflammatory cytokine TNF-α level in plasma increased and neurotrophic factor IGF-1 in plasma decreased after stroke, both of which were negatively correlated with miR-424 levels in lymphocytes or neutrophils." (PMID 29675290, 2018). "Previous reports have shown that TNF-α, IFN-γ, IL-6, IL-17, IL-23, and some monocytes are detrimental in the pathologic process of stroke, whereas Treg cells, IL-4, IL-10, and TGF-β are major cerebroprotective modulators of post-ischemic inflammatory brain damage." (PMID 27682880, 2017). "The serum levels of TNF-α, CRP, TGF-β, IL-4, IL-6, IL-10, IL-17, and IL-23 were all increased on days 1, 3, and 7 after stroke when compared with levels in the control group (all p < 0.05); however, the content of IFN-γ was lower in stroke patients than in controls at each time point (p < 0.01)." (PMID 27682880, 2017). "In DM stroke patients, microglial activation is increased within minutes of ischemia onset and triggers the production of inflammatory cytokines, including MMP9 and TNFα, which exacerbate tissue damage." (PMID 29221142, 2017). "In our investigation, results from tumor necrosis factor (TNF-α), interleukin 1 beta (IL-1β) and interleukin 6 (IL-6) assessment demonstrated that of Danshensu or HSYA treatment has an anti-inflammatory effect for stroke." (PMID 29383171, 2017). "This was in accordance with Emsley and Hopkins (2008), who reported a significant reduction of TNF-α in stroke patients with an infection relative to the non-infected." (PMID 27453748, 2016). "Transwell assays revealed that luciferase-carrying exosomes can cross a BMEC monolayer under stroke-like, inflamed conditions (TNF-α activated) but not under normal conditions." (PMID 28392840, 2016). "Similar to observations made using other brain infection and stroke models, we observed increased production of IFN-γ and TNF-α following stimulation with a recognized T-cell epitope peptide by lymphocytes obtained from the brains of DTx-treated animals when compared to untreated mice." (PMID 26720146, 2015). "National Institute of Health Stroke Scale (NIHSS); hemorheological detection; coagulation function; and serum inflammatory markers, tumor necrosis factor-alpha (TNF-α), interleukin-1β (IL-1β), and interleukin-6 (IL-6), were used to investigate the effects before and 14 days after the treatment." (PMID 26074992, 2015). "Glutamate correlated with stroke severity, but not with outcome, and TNF-alpha levels with infarct volume." (PMID 25086655, 2014). "In contrast, an anti-ICAM-1 functionalized MPIO (ICAM-MPIO) with a size of approximately 1 μm bound specifically to TNF-stimulated brain endothelial cells in vitro, and showed T2 hypointense brain areas 1 hour after induction of the transient MCAO stroke model in vivo." (PMID 25525560, 2014). "This is, in the case of TNF, different from studies of human stroke, where most but not all studies report an elevation of serum TNF from 24 to 72 hours after stroke onset." (PMID 25038795, 2014). "Since microglial-macrophage-produced TNF and SHPS-1/SIRPα are both known to have neuroprotective and pro-regenerative functions, SP-D could potentially have indirect effects on post-stroke neural plasticity." (PMID 25038795, 2014).